IL5 (interleukin 5)
Diseases named in the same sentence as IL5 in open-access papers (continued):
Sharing a sentence is not in itself a finding about the gene and the disease.
asthma (continued). "The exposure of allergens in asthma induces the release of pro-inflammatory cytokines, such as IL-5 and IL-13, and ultimately induces eosinophilic airway inflammation and increases in inflammatory mediators." (PMID 30991656, 2019). "6A4G7 showed dose-dependent inhibition of D. pteronyssinus- or Der p 2-induced IL-5 production in MoDC/CD14− PBMC co-cultures was observed in all patients with asthma (respectively)." (PMID 31861989, 2019). "Recently, therapies targeting IL-4, IL-5, and IL-13 have shown potential efficacy for treating asthma." (PMID 31114590, 2019). "Patients included in this study are extensively charactarised by comorbid allergic sensitzation, asthma, aspirin hypersensitivity, IL-5 and ECP amounts in tissue." (PMID 31249662, 2019). "In particular, concomitant increases of serum levels of IL-5 and IL-18 were found in patients with asthma, and the concentrations of these two cytokines correlated with disease exacerbations." (PMID 31920718, 2019). "CRS patients exhibiting S. aureus enterotoxin-specific IgE frequently have comorbid asthma and high mucosal Interleukin 5 (IL5) levels." (PMID 31590226, 2019). "IL-5 and IL-13, which are secreted mainly by Th2 cells and group 2 innate lymphoid cells, play important roles in the pathophysiology of asthma." (PMID 31861989, 2019). "More recently biologic therapies that target T2 pathways including IL-4, IL-13, and IL-5 have been shown to be effective in patients with asthma and nasal polyps." (PMID 31294006, 2019). "Many of these drugs target the IL-5 receptor or IL-5 cytokine; however, 4μ8c appears to target IL-5 secretion, and this makes 4μ8c of interest for the treatment of asthma due to the ability of 4μ8c to target IL-5 in established TH2 cells." (PMID 30630412, 2019). "It has since been shown that Th2 cells play a central role in the pathogenesis of asthma by secreting typical Th2 cytokines, such as interleukin (IL)-4, IL-5, and IL-13." (PMID 31216735, 2019). "IL-4, IL-5, and IL-13, while important for promoting the clearance of parasites, can promote a disease state when improperly expressed, such as with asthma and allergy, by activating immune cells involved in these pathologies." (PMID 30630412, 2019). "In horses with mild asthma, we observed a down-regulation of IL-5 in response to dexamethasone administration." (PMID 31694631, 2019). "New biologics that target IL-5 signaling (anti-IL-5 [mepolizumab, reslizumab] and anti-IL-5 receptor α [benralizumab]) reduce the rate of asthma exacerbations in patients with severe eosinophilic asthma." (PMID 30616547, 2019). "Other pharmacological strategies have been directed at modulating exaggerated Th2-type response with the use of anti-IL-5 monoclonal antibodies (mepolizumab, reslizumab, and benralizumab) in patients with asthma." (PMID 31827925, 2019). "Eos asthma is known to be associated with the Th2 pathway and IL4, IL5, and IL13 are involved in “Th2-high” asthma." (PMID 30941157, 2019). "Collectively, all these findings suggest that IL-5 affects airway physiology in asthma in part through effects on airway epithelial cells." (PMID 31885750, 2019). "Sputum eosinophils and serum periostin are biomarkers that have been proposed for defining which children with asthma will respond to anti-IgE, anti-IL-5, or anti-IL-13 asthma treatment." (PMID 31294006, 2019). "IL-5 has been extensively studied in the context of allergic disease and asthma, due to its critical role in regulating eosinophil biology." (PMID 31415658, 2019). "In experimental monkey models of asthma, IL-5 was capable of inducing bronchial eosinophilia and the consequent airway hyperresponsiveness." (PMID 31920718, 2019). "Our study observed that placenta-derived MSCs undoubtedly exerted an anti-IL-5 effect in culture, and can therefore be considered a potential treatment for asthma." (PMID 31673233, 2019).
asthma (continued). "A few pharmacogenetic studies have recently evaluated the response to asthma therapies with anti-IL-5 monoclonal antibodies, such as mepolizumab, which has been evidenced to reduce asthma exacerbations rates and enables asthma control." (PMID 30805318, 2019). "Current biologic treatments for severe asthma target a type 2-driven eosinophilic phenotype by blockade of IgE, IL-4Rα, IL-13, and, importantly, IL-5/IL-5Rα." (PMID 31415658, 2019). "These have been designed to act directly toward specific components of the T-lymphocyte inflammatory response involved in asthma such as, interleukin 5 (IL-5)." (PMID 30805318, 2019). "Anti-IL-5 monoclonal antibodies have the potential to reduce the incidence of asthma exacerbations by 50% while improving the FEV1." (PMID 31827925, 2019). "Increased circulating and sputum IL-5 and IL-13-producing ILC2s were detected in severe asthma compared to mild asthma patients." (PMID 31443563, 2019). "IL-5 is a critical mediator of eosinophil activation to promote bronchial inflammation and asthma symptoms, and IL-13 is involved in bronchial hyperreactivity and airway remodeling, such as mucus metaplasia and subepithelial fibrosis." (PMID 31861989, 2019). "Increased Th2 responses are clearly involved in the onset of asthma and other atopic conditions because IL-4 and IL-13 are required for IgE synthesis and IL-5 is necessary for the recruitment of eosinophils." (PMID 31195744, 2019). "In our study, DA-treated mice exhibited a significantly lower number of inflammatory cells in BALF than OVA-induced asthma model, and lower levels of IL-5 and IL-13." (PMID 30991656, 2019). "Our data confirm the utility of anti-IL5 therapy in a carefully selected phenotype of severe asthma with evidence of eosinophilic airway inflammation." (PMID 31861993, 2019). "A disintegrin and metalloproteinase-33 (ADAM-33), TGF-β, vascular endothelial growth factor, matrix metalloproteinase-9 (MMP-9), IL-5, IL-13, and IL-14 are key mediators involved in airway remodeling in asthma." (PMID 31284537, 2019). "We postulated that in children with asthma, the mechanism of MSCs would involve the modulation of T cell immune responses and cytokine IL-5." (PMID 31673233, 2019). "IL-5, a primary T-cell-derived cytokine, regulates eosinophil development and is regarded as a significant contributor to atopic diseases such as asthma." (PMID 31164999, 2019). "MoAbs against IL-5 reduce asthma exacerbations and thus show the potential to serve as therapeutic agents in a selected population of patients with asthma." (PMID 31861989, 2019). "Corticosteroid treatment in asthma, is associated in the downregulation of BAL cells expressing mRNA for IL-4 and IL-5 and in the upregulation of cells expressing mRNA for IFN-γ." (PMID 31001262, 2019). "In contrast, montelukast-treated mice had significantly lower levels of IL-5 in BALF than OVA-induced asthma model, and DA-treated mice had markedly lower levels of IL-5 than OVA-induced asthma model." (PMID 30991656, 2019). "Type 2 cytokines such as IL-4, IL-5, and IL-13 play a critical role in mucous cell metaplasia and mucus hypersecretion during asthma." (PMID 30654796, 2019). "The IL-5-dependency of allergen-induced airway eosinophilic inflammation in murine models of asthma was confirmed using anti-IL-5 neutralizing antibodies." (PMID 31216735, 2019). "Hinks and his colleagues revealed that IL-5 production emphasized the function of YKL-40 in severe asthma." (PMID 31001555, 2019). "Th2 cells release various proallergic inflammatory cytokines, such as IL-4, IL-5, IL-13, and GM-CSF, which activate basophils and eosinophils and increase mucus secretion in the airway in patients with asthma." (PMID 31284537, 2019). "Azithromycin down‐regulated interleukin‐5(IL‐5) production in Th2 cells isolated from asthmatic children and cultured in ex vivo, the central role of IL‐5 in the pathogenesis of asthma has been widely demonstrated." (PMID 30661297, 2019).
asthma (continued). "The importance of type 2 immune responses, characterized by the production of interleukin-4 (IL-4), IL-5, and IL-13, has received much attention in the pathogenesis of asthma." (PMID 31114590, 2019). "Circulating Tregs from individuals with allergic phenotype asthma have a reduced ability to inhibit production of Th2 cytokines (IL-5 and IL-13)." (PMID 31827925, 2019). "Those with T2-high asthma on genetic profile were found to have increased IL-13, IL-5, eosinophils, and mast cells as well as more atopy." (PMID 31294006, 2019). "These targeted immunotherapy, in particular anti-IgE and anti-IL5 antibodies, have been shown to reduce asthma severity and frequency of acute exacerbation and achieve steroid-sparing effect in patients with Th2-skewed asthma endotype." (PMID 31319491, 2019). "Increased IL-5 and IL-13 expression has been found in allergen-challenged bronchoalveolar lavage fluid cells of patients with asthma." (PMID 31861989, 2019). "Further research is thus warranted to compare IL-5 and IL-13 production in the same population before and after asthma treatment." (PMID 31861989, 2019). "The role of eosinophilia in atopic diseases, including asthma, is well established, as is the well-known role of IL-5 as a major eosinophilopoeitin and chemoattractant." (PMID 31415658, 2019). "We also found that NIP45 deficiency led to a significant decrease of the Th2 cytokines IL-4, IL-5 and IL-13, which are the principle components in the onset of asthma." (PMID 31666531, 2019). "Group 2 consists of the anti-IL-4Rα antibody, anti-IL-5 antibody, anti-IL-13 antibody, anti-IL-9 antibody, and anti-IL-17 antibody, which are the investigational drugs for asthma." (PMID 31284537, 2019). "The anti-IL-9 antibody inhibited the pulmonary infiltration of inflammatory cells and decreased the production of cytokines IL-5, IL-9, and IL-17 in murine asthma models." (PMID 31284537, 2019). "FA aggravates asthma, at least in part by increasing the T helper-2 dominant response, which is related to levels of the cytokine mediators of asthma (IL-4, IL-5, IL-9, and IL-13)." (PMID 29780828, 2018). "Clinical trials evaluating anti-IL-5 antibodies in mucosal eosinophilic disorders other than asthma." (PMID 29682504, 2018). "The first available mAb for asthma, omalizumab, was administered via the SC route, but in later clinical trials with anti-IL-5 mAbs, IV administration was used." (PMID 30115042, 2018). "The IL-4, IL-5 and IL-10 levels of allergic rhinitis, asthma and complication groups were significantly different from those of the control group (P<0.01) (Table-III).The IL-5 levels of allergic rhinitis and asthma groups were significantly different (P<0.01)." (PMID 30344593, 2018). "It has also been demonstrated that p38 MAPK pathway regulated the expression of IL-4 and IL-5 at the levels of mRNA and protein, which played a crucial role in the pathogenesis of asthma." (PMID 29554934, 2018). "The trials involved in establishing the efficacy of IL-5 pathway targeting in asthma, leading to regulatory approval, have recently been reviewed." (PMID 29682504, 2018). "Mepolizumab and reslizumab are IL-5 inhibitors that are FDA-approved for severe refractory asthma and eosinophil-mediated inflammation." (PMID 29760827, 2018). "In people with asthma, IL-33 pre-exposure led to significantly higher RV-induced (in red) IL-5 and IL-13 release (in red) compared to RV alone (in green) (p = 0.02 and p = 0.003 respectively)." (PMID 30174671, 2018). "The availability of anti-IL-5 mAbs has directed attention towards eosinophils as the main target of asthma treatment, neglecting the central role of IgE in SAA despite increasing awareness of the role of IgE in allergic inflammation." (PMID 29879991, 2018). "The IL-5 levels of allergic rhinitis, asthma and complication groups were 12.2, 9.9 and 14.2 times that of the control group (3.14 ±2.75) ng/L), respectively." (PMID 30344593, 2018).
asthma (continued). "The relatively recent discovery of IL-5, in 1980, its interaction with eosinophils, and subsequent results of anti-IL-5 blocking mAb treatment in patients with asthma confirmed the importance of IL-5 in eosinophil-mediated inflammation in humans." (PMID 29879991, 2018). "Reslizumab, targeting IL‐5, a cytokine involved in the maturation, recruitment, and activation of eosinophils, improved lung function, asthma symptoms and quality of life in two Phase 3 studies, without significant side effects." (PMID 29164823, 2018). "For patients with severe uncontrolled asthma, monoclonal antibodies (mAbs) against IgE or IL-5 are now available as add-on treatments to inhaled corticosteroid (ICS) plus long-acting β2-agonist (LABA) therapy." (PMID 29879991, 2018). "Many clinical trials have revealed that antibodies against IL-5 or IL-5 receptor, IL-13, and IL-4Rα modestly reduced asthma exacerbations and improved lung function." (PMID 30050954, 2018). "This was not replicated in MAAS3, but previous work in MAAS had identified that a strong PBMC Th2 response (IL-5, IL-13) to HDM stimulation at age 8 was associated with increased risk of HDM sensitisation and asthma." (PMID 30320550, 2018). "Novel anti-IL5 agents such as reslizumab and benralizumab were also able to reduce asthma exacerbations in clinical trials settings." (PMID 29619379, 2018). "Overall, no changes in blood leukocyte counts (besides eosinophils) have been observed in the numerous trials with anti-IL-5 for asthma and eosinophilic disorders." (PMID 29682504, 2018). "This helps to make sense of the clinical effectiveness observed with anti-IgE mAbs in bronchial asthma and the effects of anti-IL-5 mAbs in specific (eosinophilic) asthma patient populations." (PMID 29879991, 2018). "This anti-interleukin-5 antibody has been shown to reduce severe asthma exacerbations and need for oral steroids, even though evidence for its use in children < 12 years is virtually absent." (PMID 30701170, 2018). "Results showed that patients with high IL-5 levels had the highest prevalence of nasal polyps and asthma." (PMID 29564208, 2018). "Ongoing and planned clinical trials in eosinophilic disorders other than asthma using IL-5 targeted therapy." (PMID 29682504, 2018). "The most important cytokine involved in the induction, maintenance, and amplification of airway eosinophilia in asthma is interleukin-5 (IL-5), released by both T helper 2 (Th2) lymphocytes and group 2 innate lymphoid cells (ILC2)." (PMID 29862274, 2018). "IL-5, a type-2 cytokine, plays a crucial role in the initiation and growth of eosinophilic airway inflammation in asthma." (PMID 29781332, 2018). "The location of the PCDH 1 is in 5q 31-33 chromosome which is the harboring zone for several genes like Interleukin-4 (IL-4), Interleukin-5 (IL-5), Interleukin-13 (IL-13), the candidate genes for asthma and allergy traits." (PMID 30510870, 2018). "For patients with severe uncontrolled asthma, monoclonal antibodies (mAbs) against immunoglobulin E (IgE) or interleukin (IL)-5 are now available as add-on treatments." (PMID 29879991, 2018). "The present study also showed that resveratrol treatment significantly reduced the levels of Th-2 cells and Th2-related cytokines (IL-5, and IL-13) in addition to asthma-related cytokines such as TGF-β in BALF, and serum." (PMID 30619345, 2018). "Eligibility for mepolizumab was highest (78%), and greater than its anti-IL-5 counterparts benralizumab and reslizumab, although all three biologics target a similar allergic endotype of asthma." (PMID 30479629, 2018). "Allergic rhinitis and complication groups had significantly different IL-5 and IL-10 levels (P<0.05, P<0.01), and the asthma group had significantly different ILs levels from those of the complication group (P<0.01, P<0.01, P<0.05)." (PMID 30344593, 2018).
asthma (continued). "The results of present study showed that, although the concentrations of IL-5 and IL-13 were higher in asthmatic children with RV infection, it was not significantly different between mild, moderate, and severe acute asthma exacerbation." (PMID 30210646, 2018). "In accordance with these findings, anti-IL-5 mAb is now prescribed for patients with severe eosinophil-dominant asthma in the clinical setting." (PMID 30323811, 2018). "Th1 cytokines, such as IFN-γ, inhibit allergen-induced eosinophil recruitment and IgE release via downregulating GATA-3, IL-4, and IL-5 expression in the lung tissues of asthma model." (PMID 29991953, 2018). "The aim of this review is to provide a concise discussion of the various monoclonal therapies against IL-5 that are available for the treatment of asthma." (PMID 30416896, 2018). "In agreement and in line with our findings, mice with genetic deletion of either PI3Kδ or PI3Kγ are resistant to Th2-driven asthma and show reduced levels of IL-5 and IL-1339,40." (PMID 30542075, 2018). "IL-5 remains the main factor determining the phenotype with nasal polyps and asthma, thereby gaining in importance as a therapeutic target." (PMID 29564208, 2018). "Increasing levels of IL-5 and staphylococcal superantigen production seem to increase the likelihood of a phenotype of CRSwNP and comorbid asthma." (PMID 29755418, 2018). "As expected, qRT-PCR revealed that patients with asthma had significantly higher levels of IL-5 than controls (p = 0.0360 at V1 and p = 0.0115 at V2)." (PMID 30005648, 2018). "The asthma group showed a statistically significant upregulation in gene expression of IL-4 and IL-5, evaluated using the homogenate of lung parenchyma)." (PMID 29772010, 2018). "Recently, several new biological therapies targeted IgE and IL‐5 in severe asthma have been developed and approved." (PMID 30088345, 2018). "The levels of eosinophil activators CCL11 and IL-5 were significantly increased in plasma of humanized asthma control group, and CCL11 restored to normal level upon IL-37b administration (all P < 0.05)." (PMID 29988381, 2018). "Woodruff and coworkers identified the two most popular asthma subgroups, “T2-high” and “T2-low,” through the different expression of IL-5 and IL-13 transcripts in bronchial biopsies." (PMID 29992143, 2018). "Th1 cells exert a protective effect on asthma through releasing IFN-γ and IL-2, while Th2 cells mainly secrete IL-4, IL-5, and IL-13, and then promote the development of asthma." (PMID 30089474, 2018). "The objective of this observational study was to identify and describe the proportion of patients with severe asthma who were eligible for targeting IgE, IL-5, or both pathways of immunomodulation." (PMID 30479629, 2018). "In severe eosinophilic asthma, anti-interleukin (IL)-5 monoclonal antibody decreases blood eosinophil count and asthma exacerbation frequency." (PMID 30323811, 2018). "It took several years to identify the ideal candidates for IL-5 targeted therapy, based on a better understanding of asthma heterogeneity." (PMID 29682504, 2018). "Anti-interleukin (IL)-5 mAbs mepolizumab, benralizumab and reslizumab block the interaction between IL-5 and its receptor on eosinophils, thus targeting the eosinophilic pathway in asthma." (PMID 30115042, 2018). "All these IL-5 target drugs have been shown to reduce the number of exacerbation in patients with severe asthma selected on the basis of peripheral blood eosinophil count." (PMID 30498762, 2018). "Elevated eosinophilic inflammation and elevated IgE levels, as well as the release of cytokines such as interleukin-5 (IL-5) and interleukin-13, define the T2-high asthma phenotype." (PMID 30474042, 2018). "We propose to develop a vaccine against IL-5 for the treatment of asthma in humans to broaden patient access to the highly effective therapy and to facilitate long-term treatment." (PMID 30405579, 2018).